KRT19 (keratin 19)
Diseases named in the same sentence as KRT19 in open-access papers (continued):
Sharing a sentence is not in itself a finding about the gene and the disease.
non-small cell lung carcinoma (30 papers, 2004 to 2025). A group of at least three distinct histological types of lung cancer, including non-small cell squamous cell carcinoma, adenocarcinoma, and large cell carcinoma. "Elevated levels of the Cytokeratin-19 fragment (CYFRA 21-1) have been identified in patients with non-small cell lung cancer (NSCLC), suggesting its potential role as a diagnostic or prognostic marker." (PMID 41395368, 2025). "A meta-analysis showed that SHOX2 methylation had higher sensitivity (70%) and specificity (96%) than carcinoembryonic antigen and cytokeratin 19 fragment antigen 21–1 in MPE associated with non-small cell lung cancer." (PMID 37158875, 2023). "Pooled effect was calculated to evaluate the association between Cytokeratin 19 fragment level and long-term overall survival, as well as the tumor clinicopathological features in Non-small Cell Lung Cancer patients." (PMID 28008142, 2017). "Cytokeratin 19 has been described in the serum of patients with non-small cell lung cancer (NSCLC), and has been associated with tumor burden and response to therapy." (PMID 19563666, 2009). "Cytokeratin 19 is a filament protein that is abundant in epithelial cells and has been overexpressed in non-small cell lung cancer, and its overexpression is correlated with a poor prognosis." (PMID 38152395, 2023). "CYFRA-211 is a soluble fragment of cytokeratin 19, which has positive significance for the diagnosis of non-small-cell lung cancer." (PMID 31930131, 2019). "In advanced Non-small Cell Lung Cancer, the level of serum Cytokeratin 19 fragment appears to provide more prognostic information than it does for clinical Tumor Node Metastasis stage information." (PMID 28008142, 2017). "The purpose of this study was to determine the prognostic significance of a high pretreatment serum CYFRA 21-1 level (a cytokeratin 19 fragment) adjusted for the effects of well-known co-variables in non-small-cell lung cancer (NSCLC)." (PMID 15150567, 2004). "The aim of this study was to test whether carcinoembryonic antigen (CEA) and cytokeratin 19 fragments (CYFRA21-1) can be used as a prognostic factor for non-small-cell lung cancer (NSCLC) after two cycles of adjuvant chemotherapy in NSCLC patients." (PMID 23691489, 2012). "This meta-analysis evaluated whether pretherapy serum levels of carcinoembryonic antigen (CEA) and cytokeratin-19 fragments (CYFRA 21-1) are predictive of response to therapy in non-small cell lung cancer (NSCLC) and whether changes in these markers during vs pretherapy are indicative of response." (PMID 28278517, 2017). "The prognostic value of cytokeratin 19 fragment (CYFRA 21 − 1) and Ki67 in advanced non-small cell lung cancer (NSCLC) patients with wild-type epidermal growth factor receptor (EGFR) remains to be explored." (PMID 37004004, 2023). "Significantly, shorter survival rates have been associated with high levels of circulating tumor biomarkers, e.g., cytokeratin-19 fragment, neuron-specific enolase (NSE), and thymidine kinase, in patients with non-small-cell lung carcinoma (NSCLC)." (PMID 33880365, 2021). "The predictive and prognostic value of carcinoembryonic antigen (CEA), cytokeratin-19 fragments (Cyfra21-1), squamous cell carcinoma antigen (SCCA) and neuron-specific enolase (NSE) has been investigated in non-small-cell lung cancer (NSCLC) patients." (PMID 27072585, 2016). "The aim of the study was to assess the clinical prognostic value of serum cytokeratin 19 fragment (CYFRA21-1) and carcinoembryonic antigen (CEA) for non-small-cell lung cancer (NSCLC) patients." (PMID 26333429, 2015). "The pooled RR estimates indicated that there is no statistical significance of Cytokeratin 19 fragment level expression in the advanced Non-small Cell Lung Cancer (IIIB+IV) (RR =1.43, 95% CI: 0.85-2.43)." (PMID 28008142, 2017).
non-small cell lung carcinoma (continued). "This meta-analysis indicated that Cytokeratin 19 fragment high level expression correlated with lower 2-year overall survival (RR =0.47; 95%CI: 0.28-0.79), higher Tumor Node Metastasis stage (II+III+IV) (RR =1.43; 95%CI: 1.15-1.76) in Non-small Cell Lung Cancer." (PMID 28008142, 2017). "Cytokeratin 19 fragment is a negative prognosis indicator and its high level expression indicates higher Tumor Node Metastasis pathological stage (II+III+IV) in Non-small Cell Lung Cancer." (PMID 28008142, 2017). "In conclusion, the results of this meta-analysis showed that Cytokeratin 19 fragment (CYFRA 21-1) is a negative prognosis indicator and its high level expression indicates higher Tumor Node Metastasis (TNM) pathological stage (II+III+IV) in Non-small Cell Lung Cancer (NSCLC)." (PMID 28008142, 2017).
gastric cancer (29 papers, 1996 to 2025). A primary or metastatic malignant neoplasm involving the stomach. "We studied the clinical significance of the soluble cytokeratin 19 fragment detected with monoclonal antibody CYFRA 21-1 in the sera of patients with histologically proven gastric cancer." (PMID 8664124, 1996). "Many different kinds of molecular markers for the detection of peritoneal micrometastases have been described, such as conventional RT–PCR assay of CEA, keratin 19 and AFP using the peritoneal wash from gastric cancers." (PMID 14760382, 2004). "The detection sensitivity of classical biomarkers and epidemiological factors for gastric cancer was 13% (CEA), 6% (AFP), 6% (CA125), 3% (CA15-3), 14% (CA19-9), 29% (CA72-4), 36% (cytokeratin 19), 13% (NSE), 18% (overweight), 25% (smoking), 10% (alcohol) and 7% (previous history of cancer)." (PMID 28925386, 2017). "Cytokeratin-19 (CK19) has been proven to be commonly expressed by cancer cells in a variety of solid tumors and may serve as a suitable marker of metastases in gastric cancer (GC)." (PMID 32992913, 2020).
thyroid cancer (29 papers, 2008 to 2025). "Cytokeratin 19 (CK19), found in normal thyroid follicular epithelium, is upregulated during neoplastic transformation and thought to be associated with thyroid cancer aggressiveness." (PMID 38500204, 2024). "In the present study, KRT19 was found overexpressed in breast, colon, lung, liver and thyroid cancer, consistently with previous reports; KRT19 was associated with poor clinical outcomes in cancer patients as well." (PMID 36949761, 2023). "This is supported by the fact that thyroid cancer markers Cytokeratin-19 and Galectin-3 detection are strongly reduced upon MEK inhibition." (PMID 28445948, 2017). "Cytokeratin 19 was expressed in thirty-nine (97.5%) malignant thyroid neoplasms." (PMID 37455890, 2023). "To confirm the phenotype reversion found in PD-325901 treated thyroids, we performed staining for the tumor markers Cytokeratin 19 (CK19) and Galectin-3 (Gal-3), that are clinically used markers of thyroid cancer." (PMID 28445948, 2017). "In addition to galectin-3, other markers such as Hector Battifora mesothelial cell-1 (HBME-1), cytokeratin-19 (CK19), and cluster differentiation antigen 56 (CD56) can facilitate the diagnosis of thyroid carcinoma in both histologic and cytologic preparations." (PMID 37324272, 2023). "In recent years, several immunohistochemical markers, such as cytokeratin-19, galectin-3, HBME-1, fibronectin-1, and intracellular sodium/iodide symporter, or their combinations have been used to differentiate benign thyroid diseases from thyroid cancer." (PMID 27446209, 2016).
colorectal cancer (26 papers, 2000 to 2025). A primary or metastatic malignant neoplasm that affects the colon or rectum. "Keratin-19, which is positive in colorectal carcinoma, was immunohistochemically detected intercellularly in the entire tumor area." (PMID 36831399, 2023). "For the colorectal cancer patients, six out of the seven samples (85.7%) that were cytokeratin 19-positive were CD44v6-negative, whereas ten samples out of the 29 not containing epithelial cells were CD44v6-positive (34.5%)." (PMID 10755402, 2000). "In colorectal carcinoma, keratin-19 positivity is a sign of better differentiated colorectal CRC." (PMID 36831399, 2023). "Specially, KRT19 mRNA expression was upregulated in breast and colorectal cancers." (PMID 30650643, 2019). "KRT19, KRT20, and VDR, which are markers of colonic enterocytes, were increased in reverted colorectal cancer cells." (PMID 39661721, 2025). "Keratin 19 appeared to be significantly upregulated in both groups of CRLM, confirming its positivity in colorectal carcinoma." (PMID 36831399, 2023). "Another study showed that the expression of cytokeratin 19 (CK19) and RPL19 in the stool of patients with advanced colorectal cancer was significantly increased." (PMID 34350180, 2021). "The one-step nucleic acid amplification (OSNA) method quantifies cytokeratin 19 (CK19) mRNA expression, and is used in clinical practice for the diagnosis of LNM in several types of tumors, such as breast, gastric or colorectal cancer, and recently in prostate and gynaecological malignancies." (PMID 36552774, 2022).
colon carcinoma (24 papers, 2008 to 2026). "KRT19 is one of the most used markers for the detection of dissemination of tumor cells in breast, lung, and colon cancer." (PMID 36834987, 2023). "We found that KRT19 displayed high alteration frequency in numerous cancer patients and that KRT19 was frequently amplified in up to 3.5% of breast and colon cancer cases." (PMID 30650643, 2019). "As we found contrasting effects of KRT19 knockdown in breast and colon cancer cells, we compared the signaling mechanisms involved in this study." (PMID 30650643, 2019). "In colon cancer, KRT19 knockdown resulted in suppression of cancer via downregulation of Wnt/Notch signaling without altering NUMB transcription." (PMID 30650643, 2019). "Moreover, KRT19 has been detected in exosomes derived from colon tumors by RT-PCR and in circulating breast tumor cells." (PMID 36834987, 2023). "Moreover, KRT19+ colon cancer stem cells showed high radio-resistance by raising LGR5+ crypt-based columnar cells in the colon and intestines." (PMID 30650643, 2019). "We suggest the differential molecular mechanisms that might explain the contradictory roles of KRT19 in breast and colon cancer cells, which might contribute to the design of new cancer therapies." (PMID 30650643, 2019). "However, from the Oncomine and TCGA databases, we found that KRT19 was differently expressed in various cancer types; specifically, KRT19 was significantly upregulated in both breast and colon cancers." (PMID 30650643, 2019). "A total of 1940 LN from 149 pathologically assessed pN0 colon cancer patients were analysed for the amount of tumour cytokeratin 19 (CK19) messenger RNA (mRNA) with the quantitative reverse transcription loop-mediated isothermal amplification molecular assay One-Step Nucleic Acid Amplification." (PMID 27447172, 2016). "However, in colon cancer, KRT19 was validated to interact with β-catenin but not with RAC1 and then enhance the transcription function of LEF/TCF, thus promoting Notch signaling." (PMID 33767587, 2021). "However, in colon cancer, KRT19 was reported to interact with β-catenin, but not RAC1, and then enhanced the transcription function of LEF/TCF, thus promoting Notch signaling." (PMID 33767587, 2021). "Nevertheless, in colon cancer cells, despite the similar effect of KRT19 on β-catenin nuclear translocation, nuclear RAC1 levels did not decrease upon KRT19 knockdown." (PMID 30650643, 2019). "In colon cancer cells, the cytoplasmic and nuclear distribution patterns of RAC1 were maintained, regardless of whether KRT19 was knocked down." (PMID 30650643, 2019).
pancreatic ductal adenocarcinoma (21 papers, 2007 to 2025). An infiltrating adenocarcinoma that arises from the epithelial cells of the pancreas. "Background/Objectives: One study of pancreatic ductal adenocarcinoma has found expression of glypican-3 (GPC3) and cytokeratin-19 (CK19) determined by immunohistochemistry to be associated with higher stage and grade disease, with a more adverse prognosis." (PMID 39598037, 2024). "Immunofluorescence (IF) staining of human PDAC tumors showed increased expression of VIP in pancreatic ductal carcinoma cells with co-expression of cytokeratin-19 (CK19) when compared to adjacent normal tissues." (PMID 36302761, 2022). "Only one other research group studied the diagnostic potential of quantitative RT-PCR by detecting disseminated tumour cells based on cytokeratin-19 mRNA in blood, bone marrow and peritoneal lavage in patients with ductal adenocarcinoma of the pancreas." (PMID 21281486, 2011). "Western blot results showed that, compared to hTERT-HPNE, model genes including KRT7, KRT19, IGF2BP3, and CXCL5, were significantly increased in human pancreatic ductal carcinoma cell lines, PANC-1 and PL45." (PMID 37371833, 2023). "Interestingly, lack of METTL14 leading to increased expression of duct markers such as KRT19, SOX9, MEIS2 could have implications for pancreatic ductal carcinoma which is among the most lethal cancers in humans." (PMID 39322760, 2024). "For instance, analyses of liver tissues from both murine models and patients with pancreatic ductal carcinoma revealed the presence of DTCs lacking MHC I and cytokeratin 19 (CK19) expression." (PMID 41404065, 2025). "Interestingly, in both a pancreatic ductal adenocarcinoma mouse model and patients with liver metastasis, single DTCs do not express MHC-I or cytokeratin 19 (CK19)." (PMID 33738282, 2021).
Cirrhosis (20 papers, 2012 to 2025). A chronic disorder of the liver in which liver tissue becomes scarred and is partially replaced by regenerative nodules and fibrotic tissue resulting in loss of liver function. "In this study, CCN2, epithelial membrane antigen (EMA), fibroblast activation protein (FAP), and keratin 19 (K19) expression was studied in 314 HCCs (cohort 1), 42 scirrhous HCCs (cohort 2), and 36 chronic hepatitis/cirrhosis specimens by immunohistochemistry." (PMID 25126747, 2014).
intrahepatic cholangiocarcinoma (19 papers, 2013 to 2026). A carcinoma that arises from the intrahepatic bile duct epithelium in any site of the intrahepatic biliary tree. "Another promising candidate is the serum-soluble fragment of cytokeratin 19 (CK 19), CYFRA 21-1, that is associated with tumor progression and poor postoperative outcomes in patients with intrahepatic cholangiocarcinoma." (PMID 33297469, 2020). "It has been reported in many studies that serum Cytokeratin 19 fragment 21-1 (CYFRA21-1) and CA-242 have higher specificities than CA19-9 for intrahepatic cholangiocarcinoma, but they haven't been used in clinical routine examination." (PMID 32071556, 2020).
breast tumor (17 papers, 2004 to 2024). "This assay detects the expression level of cytokeratin 19 (CK19) which is present in some but not all breast tumors." (PMID 24216695, 2012).
ovarian carcinoma (17 papers, 2015 to 2025). A malignant neoplasm originating from the surface ovarian epithelium. "We finally added three proteins (WFDC2, KRT19, and FR-alpha) based on their previous association with ovarian cancer stages I–II in our modeling, or in the previous literature." (PMID 31240259, 2019). "KRT7 7, KRT18 and KRT19 are differentially expressed in circulating tumor cells in ovarian cancer patients." (PMID 29721183, 2018). "WFDC2 and KRT19 have previously been associated with ovarian cancer but RBFOX3 has not previously been identified as a potential biomarker." (PMID 39068297, 2024). "Genes that contributed to the most variation between subtypes included known biomarkers and master regulators of ovarian cancer subtypes (MUC16 and PAX8) and many keratin and cadherin genes (KRT19, KRT7, KRT8, CDH6, and CDH1)." (PMID 39131380, 2024). "Both models each had two proteins (KRT19, WFDC2 and FOL1R, MUCIN-16, respectively) overlapping with our previously published 11-biomarker panel for ovarian cancer." (PMID 35406529, 2022). "Other serum markers, which include mesothelin, matrix metalloproteinase 7 (MMP7), cytokeratin 19 fragment (CYFRA 21-1), and glycodelin, have shown encouraging performance in ovarian cancer, but mainly in clinical series." (PMID 26819954, 2015). "Furthermore, the Amniota-specific KRT8, KRT19, KRT23 and KRT80 were shown to be up-regulated in ovarian cancer." (PMID 36949761, 2023). "Keratin 19 (KRT19) is reported to be upregulated in response to the overexpression of the kallikrein related peptidase 4 (KLK4), with suggested a downstream increase of malignancy by lower sensitivity to paclitaxel treatment in ovarian cancer." (PMID 35406529, 2022). "Although the importance of the possible phosphorylation of KRT19 in serine residues has not been sought, the phosphorylation in serine residue 14 has found hyperphosphorylated in breast, colon, ovarian cancer, lung adenocarcinoma, and uterine corpus endometrial carcinoma (UCEC)." (PMID 32337254, 2020). "The aim of this study was to investigate whether other ovarian cancer-related biomarkers, Human Epididymis 4 (HE4), glycodelin, mesothelin, matrix metalloproteinase 7 (MMP7), and cytokeratin 19 fragment (CYFRA 21-1), could improve the performance of CA125 in detecting ovarian cancer earlier." (PMID 26819954, 2015).
cervical carcinoma (16 papers, 2010 to 2024). A carcinoma arising from either the exocervical squamous epithelium or the endocervical glandular epithelium. "The expression of four different biomarkers, namely HMGB1, SCCA/SerpinB3, CEA, and CYFRA 21-1/Cytokeratin 19, in the serum of 36 cervical cancer patients was interpreted upon SDS PAGE and western blotting." (PMID 39583399, 2024). "Our results identified the phosphorylation of KTR19 in serine residues; despite this, more extensive research is needed to determine the probable role that phosphorylated KRT19 plays in the progression of cervical cancer." (PMID 32337254, 2020). "Also, IPA diseases analysis data showed 8 proteins were associated with cervical cancer, including ANX1, ANX2, ANX 5, ENO1, HSP90AB1, YWHAE, TFRC, HSP90, and KRT19." (PMID 23243437, 2012). "KRT7 and KRT19 staining of lymph nodes is reported to have a potential in detecting micrometastatic foci in regional lymph nodes of patients with GBC and cervical cancer respectively." (PMID 37142981, 2023).
metastatic tumors (16 papers, 2003 to 2025). "However, key MMP remodeling-associated genes PLAU and MMP10 and basal cell marker KRT19 were uniquely shared upregulated genes in metastatic tumors (MET and PRI+)." (PMID 35480116, 2022). "Histopathology analysis and cytokeratin-19 immunostaining of 3 KC metastatic tumors and of representative KCATMΔ+ (n = 6) and KCATMΔΔ (n = 5) tumors identified invasive PDAC with focal or extensive desmoplasia and variable morphology in all specimens." (PMID 28894253, 2017). "Furthermore, increased epithelial cancer cells (cytokeratin 19-positive cells) and cell proliferation (Ki67, proliferation index) were observed from the lymph node tissue, providing the strong evidence of development of metastatic tumour in lymph node tissues." (PMID 40359628, 2025). "Human-specific gene expression of SNAI1, GSC, FOXC2, KRT19, and STAM2, presumably originating from DTCs, was detected in the BM of all xenograft mice that also developed metastatic tumors." (PMID 29291741, 2018).